TLR2 (toll like receptor 2)
Diseases named in the same sentence as TLR2 in open-access papers (continued):
Sharing a sentence is not in itself a finding about the gene and the disease.
rosacea (continued). "Exposure to UV radiation and Demodex mites activates Toll-like receptor 2 (TLR2), leading to the activation and subsequent release of cathelicidin—an antimicrobial peptide integral to the pathogenesis of rosacea." (PMID 39136023, 2024). "Increased expression levels of cathelicidin, kallikrein-related peptidase 5 (KLK5), toll-like receptor 2 (TLR-2), and matrix metalloproteinase (MMP) have been observed in patients with rosacea." (PMID 39044833, 2024). "TLR2, KLK5, cathelicidin peptides, and CD68 are all highly expressed in patients with rosacea and rosacea animal models." (PMID 38193038, 2023). "In LL37-induced rosacea-like mice, ART and its derivatives significantly inhibited the expression of pro-inflammatory factors (IL-1β, IL-6, and TNFα) and TLR2." (PMID 35950034, 2022). "Studies have confirmed that the expression of TLR2 and LL37 in the skin of rosacea patients is significantly increased." (PMID 33545988, 2021). "Skin samples of patients with rosacea were subjected to histopathological (hematoxylin and eosin) and immunohistochemical (CD68, Toll-like receptor 2 (TLR2), kallikrein 5, cathelicidin, TNF-α, and IL-1β) evaluation." (PMID 34322115, 2021). "PF promoted SOCS3 expression in RAW 264.7 cells and inhibited the LPS-induced increase in toll-like receptor 2 and LL37 expression through the ASK1-p38 cascade, thereby alleviating the macrophage-related rosacea-like inflammatory response." (PMID 33545988, 2021). "In vitro, carvedilol decreased TLR2 expression in RAW 264.7 cells, further reducing KLK5 secretion and LL-37 expression and ultimately inhibiting rosacea-like inflammatory reactions." (PMID 34322115, 2021). "Accumulating evidence points to activated cellular pattern recognition receptors, such as toll-like receptor 2 (TLR2), transient receptor potential ion channels, and inflammatory mediators as actors of critical steps in the clinical diagnosis of rosacea." (PMID 32185228, 2020). "The upregulation of TLR2 and S100A9 may promote the pathogenesis of rosacea and inflammatory reaction." (PMID 39823143, 2025). "Thus, TLR2 and S100A9 play important roles in the inflammatory reactions and immune regulation of rosacea." (PMID 39823143, 2025). "The aberrant function of TLR2 and the antimicrobial peptide LL37 leads to dysregulation of the innate immune system and promotes a downstream inflammatory cascade as an important mechanism in the pathogenesis of rosacea." (PMID 39692542, 2024). "In this study, we provided evidence that except microbial or host injury products, TLR2 might also recognize excess cathelicidin LL37 derived from local cells to activate mTORC1 signaling and thus trigger inflammation in rosacea." (PMID 33734592, 2021). "Abnormal functioning of TLR2 and cathelicidin LL37 may contribute to the dysregulation of the innate immune system and promote inflammatory cascade in rosacea." (PMID 33734592, 2021). "Moreover, TLR2, KLK5, cathelicidin peptides, and CD68 were highly expressed in both patients with rosacea and rosacea-like animals." (PMID 34322115, 2021). "Specifically, TLR2 and TLR4 have been shown to be overexpressed in rosacea skin." (PMID 34322115, 2021). "Moreover, TLR2 expression is increased and stimulates KLK5 production by keratinocytes in patients with rosacea." (PMID 34322115, 2021). "Here, we found that mTORC1 signaling is hyperactivated in rosacea and regulates cathelicidin via a positive feedback loop, in which cathelicidin LL37 stimulates mTORC1 signaling through binding to TLR2, thereby in turn promotes cathelicidin expression itself in human keratinocytes." (PMID 33734592, 2021). "The results of CD68 and TLR2 immunofluorescence staining showed that in the LL-37+CMC-Na group, rosacea-like inflammatory skin expressed more TLR2 on the surface of aggregated macrophages whereas this was significantly reduced on the surface of macrophages in the LL-37+carvedilol group." (PMID 34322115, 2021).
rosacea (continued). "Sensory nerves also express the neuro-inflammatory TLR-2 and PAR2 which might perpetuate the neurovascular dysregulation observed in rosacea." (PMID 30631431, 2018). "Notably, TLR-2 and probably PAR2 are upregulated in patients with rosacea, andin vitro activation of both receptors promotes the activation of cathelicidin, an anti-microbial peptide that is also overexpressed in patients with rosacea 30,31." (PMID 30631431, 2018). "Pathophysiology of Rosacea is strictly related to the abnormal expression of cathelicidins antimicrobial peptides, the elevated levels of stratum corneum tryptic enzymes (SCTE), and the expression of higher amounts of Toll-like receptor 2 (TLR2) in skin." (PMID 30006754, 2018). "A direct link amongDemodex mites, microbes, and PAR2 or TLR-2 has not yet been demonstrated in rosacea." (PMID 30631431, 2018). "In in vitro experiments, the study found that TLR2 and S100A9 protein levels increased in HaCaT cells under conditions simulating rosacea, and the cytokines IL6, OSM, and TNF‐α were significantly elevated, implying their potential promoting roles in the progression of rosacea." (PMID 39823143, 2025). "Elevated levels of disease characteristic factors, such as KLK5, CAMP, TLR2, and proinflammatory cytokines (such as TNF‐α, IL1β, and IL6), and MMPs have been observed in the skin lesions of human rosacea patients as well as in a mouse model of rosacea induced by LL37." (PMID 39692542, 2024). "Abnormal functioning of TLR-2, KLK-5, and cathelicidin or vitamin D response along with epidermal barrier disruption may contribute to the dysregulation of innate immunity and augment the inflammatory cascade in rosacea." (PMID 27649161, 2016). "Besides TLR2, our RNA‐sequencing data also showed that other TLRs (e.g., TLR4, TLR7, and TLR8) were also significantly increased in rosacea, but the role of these TLRs remains unclear in the pathogenesis of rosacea." (PMID 33734592, 2021). "External triggers: RNA sequencing revealed alteration of gene expression levels such as TLR2 and TRPV in samples from rosacea patients compared to non-lesional skins or healthy skin controls." (PMID 39136023, 2024). "The upstream signal or signals of enhanced PAR2, TLR-2, and KLK-5 proteins in rosacea have not been identified yet." (PMID 30631431, 2018).
hepatocellular carcinoma (42 papers, 2012 to 2025). A malignant tumor that arises from hepatocytes. "In the human TLR2, for example, synonymous mutations have been identified which are associated with resistance to liver cell carcinoma." (PMID 25496717, 2014). "K(D)-la has been implicated in gene regulation; for example, it modifies histones to suppress TLR2 expression, thus inhibiting hepatocellular carcinoma (HCC) progression." (PMID 40720394, 2025). "As a ligand for TLR2 and TLR4, extracellular HSPA1A potently stimulates proliferation and inhibits apoptosis in hepatocellular carcinoma cells via TLR2 and TLR4 signaling pathway and activation of nuclear factor-κB (NF-κB)." (PMID 38646439, 2024). "Studies in hepatocellular carcinoma showed that TLR2 was involved in the immune escape initiated by HMGB1 and induced the senescence and autophagy of hepatocytes." (PMID 37153547, 2023). "Previously, it was shown how miR-143 downregulates TLR2 expression in hepatoma cells, leading to the inhibition of hepatoma cell proliferation." (PMID 37822929, 2023). "Hepatoma-derived toll-like receptor 2 (TLR2)-related ligands can trigger the M2 macrophage polarization through the RelA/NFKB pathway by autophagy." (PMID 36814780, 2023). "TLR2 activation by hepatoma factors results in autophagy augmentation and the M2 immunosuppressive differentiation of TAMs." (PMID 37189787, 2023). "The positive correlation between TLR2 (toll‐like receptor 2) expression and other proliferation and angiogenesis markers in hepatocellular carcinoma suggests a possible role for TLR2 in the pathogenesis of HCC." (PMID 35293027, 2022). "In conclusion, our study determined the prognostic and immunological roles of necroptosis‐related molecules such as TRAF2, PGAM5, ATG16L1, CADR9, PCYT1A, PARP2 and TLR2 in hepatocellular carcinoma." (PMID 35293027, 2022). "Our previous studies have revealed that a Toll-like receptor 2 (TLR2)-dependent autophagy triggered by hepatoma-derived factors down-regulates NF-κB p65 and drives M2 macrophage differentiation." (PMID 32788720, 2020). "Hepatoma-derived HMGB1 stimulates NOX2-dependent ROS generation via TLR2 to trigger autophagy formation, which leads to lysosomal degradation of NF-κB p65 and hence maintains the M2 macrophage polarization." (PMID 32788720, 2020). "In this study we show that hepatoma-derived HMGB1 stimulates ROS via the TLR2/NOX2 axis to trigger autophagy-regulated M2 macrophage polarization." (PMID 32788720, 2020). "Here, we uncovered a new regulatory mechanism of the HMGB1-triggered TLR2/NOX2/autophagy axis in hepatoma-prompted M2 macrophage polarization." (PMID 32788720, 2020). "Our previous studies and those of other research groups showed that TLR2 activation in human hepatoma cells and primary woodchuck hepatocytes leads to reduction of HBV and WHV replication in vitro." (PMID 30008718, 2018). "NO, Arg-1 and SCOS3 were induced in hepatoma-treated TLR2−/− BMDM." (PMID 37925462, 2023). "In HCC, hepatoma-derived factors expressed by tumor cells could bind to hepatoma-derived toll-like receptor 2 (TLR2) to active canonical NF-κB signaling pathway." (PMID 34566989, 2021). "TLR2 has been correlated with the inhibition of HBV replication in human hepatoma cells." (PMID 29320990, 2018). "Furthermore, another study has demonstrated that the TLR2-dependent signaling from hepatoma-conditioning medium mediates p65/RelA lysosomal degradation." (PMID 29044191, 2017). "Thus, we have demonstrated specific siRNA-directed knockdown of the TLR2 gene in the human hepatocellular carcinoma cell line BEL-7402, and shown that sh-TLR2 RNAi(B) was the most efficient recombinant plasmid in silencing TLR2." (PMID 22815694, 2012). "Another study demonstrated that miR-143 could inhibit its potential target gene TLR2 in hepatoma." (PMID 39018487, 2024). "The present study aimed to investigate the temporal relationship of single nucleotide polymorphisms (SNP) of TLR2/TLR9 and the risk of hepatocellular carcinoma (HCC)." (PMID 22309608, 2012).
hepatocellular carcinoma (continued). "Wild-type (WT) and TLR2 knockout (KO) mice at 2 weeks of age were injected intraperitoneally (i.p.)with a single dose of diethylnitrosamine (DEN) to induce hepatocellular carcinoma (HCC)." (PMID 40264769, 2025). "TLR-2 and−4 activation triggers IFN-independent pathways and leads to a robust inhibition of hepadnaviral replication by various intracellular pathways in hepatoma cells and woodchuck hepatocytes harboring woodchuck hepatitis virus (WHV)." (PMID 32117201, 2019). "This study aimed to determine the expression of TLRs 1–10 in the established human hepatocellular carcinoma cell line BLE-7402, to investigate the biological effect of TLR2 on cell growth and survival." (PMID 22815694, 2012). "TLR2 stimulation leads to activation of cellular pathways including MAPK-ERK, AKT, and NF-κB signaling and suppression of hepadnaviral replication in hepatocytes and hepatoma cells." (PMID 30008718, 2018). "Notably, in hepatocellular carcinoma (HCC), HMGB1 drives M2 macrophage polarization via the TLR2/NOX2/autophagy axis, accelerating tumorigenesis." (PMID 41354099, 2025). "Similarly, in hepatocellular carcinoma (HCC), tumor-derived HMGB1 engages TLR2 on macrophages, triggering a NOX2/ROS-dependent autophagic response that drives M2 macrophage polarization, thereby creating an immunosuppressive and pro-tumorigenic niche." (PMID 41465435, 2025).
fungal infection (40 papers, 2014 to 2025). "The critical involvement of TLR2 in the recognition of C. albicans by PBMO suggests that reduced innate immune sensitivity might be responsible for the enhanced susceptibility of preterm neonates to fungal infection." (PMID 27870876, 2016). "The role of TLR2 in fungal infections has also been explored, particularly in the context of invasive fungal diseases." (PMID 41295183, 2025). "infection significantly increased PD-L1 expression in OSCC cells through the TLR2/MyD88 and NF-κB pathways, linking fungal infection to chronic-inflammation-driven immune suppression." (PMID 40278081, 2025). "The relevance of TLR2 rs1339 and rs7656411 polymorphisms to the susceptibility of AIDS patients to TM provides a new understanding of the role of TLR in fungal infections and lays a theoretical basis for the risk prediction of TM." (PMID 33777838, 2021). "In some fungal infections such as aspergillosis, TLR2 activation promotes increased phagocytosis and cytokine production." (PMID 31824444, 2019). "One study reports that an Asian KID syndrome patient with fungal infection expressed only a lower level of TLR2 mRNA57." (PMID 30150638, 2018). "TLR2 does associate with other innate signaling molecules for responses to phagocytosed microbes, but with regard to fungal infection, dimerization of TLR2 with TLR1 or TLR6 is the only requirement." (PMID 25674081, 2015). "TLR2 in mammals is required for induction of inflammatory reactions in response to fungal infection based on the rapid recruitment of fungi and fungal fragments to the macrophage phagosome." (PMID 25674081, 2015). "Thus, we predict that CLEC2D forms homodimers or heterodimers with TLR2 to negatively regulate IL-12 production during fungal infections." (PMID 37872182, 2023). "The immunomodulatory activity of the TLR2 agonist (Pam3CSK4 or P3C4) has not been evaluated as an adjuvant associated with an immunization protocol to combat fungal infections." (PMID 36743957, 2023). "While there is limited knowledge on the modulation of anti-inflammatory processes by microglia in the setting of fungal infections, a previous study had shown that, an infection with C. albicans (in mice) induces immunosuppression by activating TLR-2, leading to the release of IL-10." (PMID 32899547, 2020). "ArtinM binds directly to TLR2 N-glycans on macrophages inducing the production of cytokines such as IL-12 and IL-23, which drive the immune response to Th1 and Th17 axis and favor protection against fungal infections." (PMID 32208440, 2020). "Since P. brasiliensis yeasts induce IL-8 secretion in A549 cells in α3 integrin-9 and TLR2-dependent manners, we analysed whether these two receptors interact with each other during fungal infection." (PMID 33173103, 2020). "By interacting with cell wall components, TLR2 is frequently related to fungal infections." (PMID 33173103, 2020). "According to previous literature, the recognition of P. brasiliensis yeasts by PMNs involves different cell surface receptors, including dectin-1, mannose receptor (MR), and TLR2 or TLR4, which act collaboratively to provide mechanisms of resistance or susceptibility to fungal infection." (PMID 31886295, 2019). "The lectin ArtinM targets TLR2 N-glycans on macrophages, induces cytokines production, and promotes T helper-1 immunity, a process that culminates in resistance to several parasitic and fungal infections in vivo." (PMID 28765651, 2017). "In addition to TLR2, other TLRs, such as TLR4, have been implicated in the innate recognition of fungal infection." (PMID 26091522, 2015). "Moreover, we observed that expression of TLR2 and TLR4 was significantly higher in patients with AML and bacterial infection in comparison with group with separate fungal infection (ΔCt TLR2 1.15 ± 1.06 vs 0.66 ± 0.51 and ΔCt TLR4 0.45 ± 0.38 vs 0.21 ± 0.19)." (PMID 25412934, 2014). "Additionally, CD14, TLR1, and TLR2 have been investigated in fungal infection models before." (PMID 40098951, 2025).
fungal infection (continued). "Moreover, we analysed whether TLR2 interacts with α3 integrin and modulates its expression in A549 cells during this fungal infection." (PMID 33173103, 2020). "Furthermore, demonstrated in vitro and in vivo that the lack of TLR2 usage and signaling resulted in a less-severe fungal infection, despite the fact that TLR2 deficient and normal mice showed equivalent survival times." (PMID 26543326, 2015). "Our network pharmacology analysis predicted that XBJ regulates type I interferon and its upstream regulators such as interferon α, TLR2, and TLR4 in invasive fungal infection." (PMID 31969817, 2019). "PCN was shown herein to be efficient also as a therapy against the ongoing mycosis, and the observed Th1 immunity was attributed to PCN interaction with N-glycans of TLR2 and TLR4." (PMID 25474158, 2014). "Additionally, Dectin-1 (Clec7a) and TLR2 important PRRs in PCM and others mycosis were also observed with a transcript expression in the granuloma." (PMID 37868350, 2023). "Toll-like receptors (TLR2, TLR4), pro-inflammatory cytokines [tumor necrosis factor, interleukin 6 (IL-6), IL-1, and interferons], nuclear factor κB signaling, and HMGB1 were among top upstream regulators of the targets in fungal infection." (PMID 31969817, 2019). "It has been reported that induction of Tc17 phenotype by CD8+ cells following fungal infections is dependent on Tlr2 and MyD88, while induction of Tc1 phenotype is not." (PMID 27252700, 2016). "However, there are few studies on the effects of TLR2 and TLR4 activation during the course of this fungal infection." (PMID 27458431, 2016). "TLR2 and TLR4 are known to be involved in the host innate immune response to fungal infection." (PMID 26039076, 2015). "Moreover, we observed that expression of TLR2 and TLR4 was significantly higher in patients with AML and bacterial infection in comparison with the group with isolated fungal infection." (PMID 25412934, 2014). "In this work, the authors suggest that other receptors like TLR-2 and Dectin-1 may also contribute to the immune response during S. schenckii infection, but they assign TLR-4 an important role in governing the functions of macrophages in fungal infection." (PMID 34358055, 2021). "However, fungal infection is commonly recognized via the TLR2, TLR4 and TLR6 signaling pathways and does not result from the secretion of IFN-I." (PMID 24660033, 2014). "MyD88 is also essential for TLR2 and TLR4 signaling, yet the role of TLR2 and TLR4 is not clear in the development of corneal opacification; TLR4−/− mice have an impaired ability to clear the infection so TLR4−/− is important in eradicating fungal infection." (PMID 28324534, 2015).